RNU6-160P (RNA, U6 small nuclear 160, pseudogene)
Gene: Small nuclear RNA gene on chromosome 1 (153,331,622 to 153,331,728, forward strand). Ensembl gene ENSG00000207321.
Homologues: Orthologues: chimpanzee U6 (99% identical), macaque U6 (94% identical), guinea pig U6 (69% identical), rat LOC120101204 (67% identical), rat LOC120094869 (65% identical), pig U6 (64% identical), mouse Gm54461 (60% identical). Paralogues in human: RNU6-19P (87% identical), RNU6-20P (87% identical), RNU6-15P (86% identical), RNU6-211P (86% identical), RNU6-259P (86% identical), RNU6-35P (86% identical), RNU6-393P (86% identical), RNU6-41P (86% identical), RNU6-1060P (85% identical), RNU6-1145P (85% identical), RNU6-1152P (85% identical), RNU6-1316P (85% identical), and 1286 more.